CEP89 (centrosomal protein 89)
Description:
Required for ciliogenesis. Also plays a role in mitochondrial metabolism where it may modulate complex IV activity.
Synonyms: Cep123; CCDC123; FLJ14640
Tractability: PROTAC: ubiquitination databases record sites on it.
Gene: Protein-coding gene on chromosome 19 (32,875,925 to 32,971,992, reverse strand). Ensembl gene ENSG00000121289.
Subcellular location: Cytoplasm, cytosol; Cytoplasm, cytoskeleton, microtubule organizing center, centrosome; Cytoplasm, cytoskeleton, spindle pole; Cytoplasm, cytoskeleton, microtubule organizing center, centrosome, centriole; Mitochondrion intermembrane space
Subcellular location (Human Protein Atlas): Cytosol; Basal body; Centrosome; Primary cilium
Pathways (Reactome):
Organelle biogenesis and maintenance: Anchoring of the basal body to the plasma membrane
Gene Ontology:
Molecular function: protein binding
Biological process: cilium assembly; mitochondrial respiratory chain complex IV assembly; non-motile cilium assembly; mitochondrion organization; chemical synaptic transmission
Cellular component: centriole; centrosome; ciliary basal body; ciliary transition fiber; cytosol; mitochondrial intermembrane space; non-motile cilium; spindle pole; motile cilium; synapse
Genetic constraint (gnomAD): Loss-of-function variants: 54 observed, 57.77 expected, observed/expected ratio (o/e) 0.93, 90% interval 0.75 to 1.17. The upper end of that interval is the gene's LOEUF score, 1.17, which puts it in group 5 of 6, group 1 being the genes least tolerant of losing a copy. Missense variants: 620 observed, 681.88 expected, observed/expected ratio (o/e) 0.91, 90% interval 0.85 to 0.97. Synonymous variants: 265 observed, 265.05 expected, observed/expected ratio (o/e) 1, 90% interval 0.9 to 1.11.
Gene-disease validity (ClinGen):
ClinGen rates the evidence that CEP89 causes each of these diseases.
mitochondrial disease (autosomal recessive): Disputed.
Homologues: Orthologues: chimpanzee CEP89 (99% identical), dog CEP89 (76% identical), macaque CEP89 (71% identical), rabbit CEP89 (70% identical), mouse Cep89 (70% identical), rat Cep89 (69% identical), pig CEP89 (67% identical), guinea pig CEP89 (63% identical), tropical clawed frog cep89 (47% identical).
Diseases named in the same sentence as CEP89 in open-access papers:
CEP89 is named in the same sentence as 8 diseases in open-access papers, as found by Europe PMC text mining. Sharing a sentence is not in itself a finding about the gene and the disease. The quoted sentences say what the papers report.
ovarian carcinoma (2 papers, 2023 to 2025). A malignant neoplasm originating from the surface ovarian epithelium. "A recent paper describes how increased CEP89 copy number and expression correlates with a worse prognosis in ovarian cancer, which we hypothesise could be linked to Cep89’s role in modulating G0 arrest." (PMID 37221612, 2023). "Some studies have shown that CEP89 is upregulated in ovarian cancer, suggesting its potential as a therapeutic target." (PMID 40297177, 2025).
autosomal dominant polycystic kidney disease (1 paper, 2025). Autosomal dominant form of polycystic kidney disease. "Additionally, genetic defects in CEP89 are associated with autosomal dominant polycystic kidney disease (ADPKD), providing new insights into its molecular pathogenesis." (PMID 40297177, 2025).
breast carcinoma (1 paper, 2023). "In external validation datasets, these associations, including deletions in PTEN and LRP1B or amplifications of MYC, CEP89 and ETV6, featured most prominently in the largest cohort of breast cancer samples." (PMID 37221612, 2023).
lung adenocarcinoma (1 paper, 2023). A carcinoma that arises from the lung and is characterized by the presence of malignant glandular epithelial cells. "We validated this target in the lung adenocarcinoma cell line NCI-H1299 showing high levels of CEP89 amplification." (PMID 37221612, 2023).
prostate carcinoma (1 paper, 2025). A carcinoma that arises from epithelial cells of the prostate gland. "Current research on SPEG, ASPSCR1, and CEP89 in prostate cancer is relatively limited." (PMID 40297177, 2025).
tumour (3 papers, 2009 to 2023). "Our model linked CEP89 amplification with fast cycling tumours." (PMID 37221612, 2023). "Indeed, CEP89 amplified tumours presented elevated expression of a previously reported centrosome amplification signature (CA20), which was strongly anticorrelated with G0 arrest levels." (PMID 37221612, 2023). "Thus, we propose CEP89 as a novel cell proliferation regulator that may be exploited in certain scenarios to control tumour growth." (PMID 37221612, 2023).
cancer (2 papers, 2016 to 2023). A tumor composed of atypical neoplastic, often pleomorphic cells that invade other tissues. "Furthermore, CEP89 expression was prognostic across multiple cancer tissues and linked with toxicity of several cancer compounds in cell line models." (PMID 37221612, 2023). "Elucidating the function of Cep89 and other validated candidates with putative roles in metabolism, e.g. CG3011, CG6084 and Fbp2, whose human ortholog has been linked to growth defects and cancer [e." (PMID 26751788, 2016). "We focused on the impact of CEP89 activity on proliferation/arrest decisions due to the high ranking of this putative oncogene in the model, the relatively unexplored links between CEP89 and cell cycle control, as well as its negative association with G0 arrest across a variety of cancer cell lines." (PMID 37221612, 2023).
CEP89 also shares sentences with these, for which no sentence is quoted: glioblastoma (1 paper).